LINC-ROR (long independently transcribed non-coding RNA, regulator of reprogramming)
Diseases named in the same sentence as LINC-ROR in open-access papers (continued):
Sharing a sentence is not in itself a finding about the gene and the disease.
cancer (continued). "Overall, these findings revealed that linc-ROR might provide a novel therapeutic target and biomarker for cancers in the future." (PMID 32850817, 2020). "Furthermore, both tumorigenesis and metastasis have been shown to be induced by linc-ROR via activation of the EMT in various cancers." (PMID 32850817, 2020). "They described that linc-ROR expression was enhanced in the hypoxic cancer cell-derived exosomes." (PMID 32503591, 2020). "Moreover, both cell proliferation and migration have been reported to be promoted by linc-ROR in several types of cancers." (PMID 32850817, 2020). "Furthermore, increasing studies have shown that the molecular mechanism, such as Wnt/β-catenin signaling pathway involved in the progress of cancer, was regulated by linc-ROR." (PMID 32850817, 2020). "Downregulation of LINCROR by miR-145 might impair the cancer stemness by deregulation of another transcription factor KLF4." (PMID 29719612, 2018). "All the evidence intrigued us to speculate that Linc-ROR might also have a role in cancer progression and we found several studies have focused the role of Linc-ROR in the development of cancers, including breast cancer." (PMID 29549263, 2018). "As enhanced cancer cell motility and consequent invasion and metastasis have been associated with the gain of CSC properties and EMT, we investigated the effect of linc-ROR inhibition on these phenotypes." (PMID 29237490, 2017). "Recent studies have demonstrated that linc-ROR dysregulation may be involved in carcinogenesis as well as cancer progression in several solid tumors." (PMID 29237490, 2017). "Moreover, the molecular details and some recent papers have been omitted or partially reported, thus the importance of this review aimed to contribute to the up-to-date understanding of linc-ROR and its implication in cancer tumorigenesis, progression, metastasis, and chemoresistance." (PMID 36827545, 2023). "In conclusion, our results demonstrated that Curcumin suppressed the cell proliferation via the down-regulation of lincROR and inactivation of Wnt/β-catenin signaling, suggesting that it may be a potential anti-cancer candidate for HCC patients with activated Wnt/β-catenin signaling." (PMID 32714183, 2020). "Thus, CRISPR/Cas9 might be used to treat cancers by regulating the expression of linc-ROR via the relevant molecular mechanism." (PMID 32850817, 2020). "However, the exact molecular mechanism by which linc-ROR plays a role in various cancers remains unclear." (PMID 32850817, 2020). "Current evidence have strongly indicated that linc-ROR may exert an impact on a variety of cancers." (PMID 32850817, 2020). "Importantly, linc-ROR has a potential role in the diagnosis of cancer." (PMID 33163123, 2020). "Therefore, there’s a good chance that the technology of CRISPR/Cas9 could be used to treat cancers by editing the expression level of linc-ROR." (PMID 32850817, 2020). "Indeed, knocking down linc-ROR in both types of cancer cells rendered formation of smaller tumors." (PMID 30250400, 2018). "The colon-specific activity of the CEA promoter was assessed by evaluating the expression of MEG3 and linc-ROR in HCT116, SW480, and HeLa cancer cells." (PMID 39108882, 2024). "LncRNAs play key roles in tumorigenesis and many aspects of cancer development; therefore, evaluating the probable correlation between LINC-ROR and SALL4 in GC development is needed." (PMID 33745265, 2021).
cancer (continued). "Here we selected six candidate cancer-related lncRNAs (ZFAS1, PRNCR1, GAS5, TUG1, linc-ROR, and H19) through articles that were previously reported to be dysregulated in cancer." (PMID 29559565, 2018). "Taken together, these studies imply that linc-ROR and SOX9 are involved in stem/progenitor cell maintenance, but their roles in regulating cancer development remains to be explained." (PMID 29237490, 2017). "The long intergenic non-protein coding RNA lincROR has been shown to play a significant role in the tumorigenesis of various cancers." (PMID 39546475, 2024). "It has been demonstrated that LINC-ROR regulates the pluripotency levels of TFs, including SALL4, LIN28, OCT4, SOX2, and NANOG via acting as a miRNA-145 sponge, leading to the preservation of hESCs and cancer stem cells undifferentiated status." (PMID 33745265, 2021). "Induction of EMT via the deregulation of LINC-ROR may activate the expression of stemness marker, SALL4, as a TF with an oncogenic role in GC, to promote cancer phenotype." (PMID 33745265, 2021). "Interestingly, exosomes from the PTC cancer stem cell (PTC-CSC) model were transferred beside the transcription factors SLUG and SOX2, the lncRNA MALAT1, and the linc-ROR resulting to the induction of EMT." (PMID 35186709, 2021). "Although linc-ROR has been reported in a few types of cancers, but the roles of it in LAD carcinogenesis are still not understood." (PMID 28388536, 2017). "The observation that linc-ROR and SOX9 are coordinately expressed in ESCC tissues led to the hypothesis that linc-ROR might promote stem cell-like properties and cancer progression through the regulation of pluripotency transcription factor SOX9." (PMID 29237490, 2017). "Although it is of crucial importance to understand the molecular pathways by which linc-ROR exerts its positive and negative effects in cancer, the clinicopathological implications must be widely explored to offer practical diagnostic, prognostic, and treatment alternatives." (PMID 36827545, 2023). "However, cancer-related molecular mechanisms, its functional roles, and clinical value of LINC-ROR in GC remain unclear." (PMID 33745265, 2021). "LINC-ROR stimulates cancer stem cell phenotype and ESCC progression through the deregulation of SOX9, as a TF involved in embryogenesis and maintenance of stem/progenitor cells, to coordinately promote cell proliferation, motility, self-renewal capacity, and cancer stemness state." (PMID 33745265, 2021).
LINC-ROR also shares sentences with these, for which no sentence is quoted: esophageal squamous cell carcinoma (5 papers); prostate carcinoma (3); retinoblastoma (3); atherosclerosis (2); cardiac hypertrophy (2); dermatitis (2); renal cell carcinoma (2); acute myeloid leukemia (1); acute renal failure (1); anaemia (1); anaplastic thyroid carcinoma (1); Arthritis (1); bipolar disorder (1); central nervous system lymphoma (1); cervical cancer (1); dysplasia (1); head and neck squamous cell carcinoma (1); heart failure (1); hepatopulmonary syndrome (1); hypertrophic cardiomyopathy (1); immune disorders (1); infection (1); melanoma (1); metabolic syndrome (1); metastasis (1); myelosuppression (1); myocardial infarction (1); ocular melanoma (1); oral cancer (1); Oral ulcer (1).
A further 8 diseases each share a sentence with LINC-ROR in 1 paper.